SLC29A2 (solute carrier family 29 member 2)
Description:
Bidirectional uniporter involved in the facilitative transport of nucleosides and nucleobases, and contributes to maintaining their cellular homeostasis. Functions as a Na(+)-independent, passive transporter. Involved in the transport of nucleosides such as inosine, adenosine, uridine, thymidine, cytidine and guanosine. Also able to transport purine nucleobases (hypoxanthine, adenine, guanine) and pyrimidine nucleobases (thymine, uracil). Also mediates nicotinamide uptake supporting homeostasis and modulating its biological activities. Can also transport urate. Involved in nucleoside transport at basolateral membrane of kidney cells, allowing liver absorption of nucleoside metabolites. Mediates apical nucleoside uptake into Sertoli cells, thereby regulating the transport of nucleosides in testis across the blood-testis-barrier. Mediates both the influx and efflux of hypoxanthine in skeletal muscle microvascular endothelial cells to control the amount of intracellular hypoxanthine available for xanthine oxidase-mediated ROS production (By similarity). [Isoform 3]: Non functional nucleoside transporter protein for adenosine or thymidine transport. Does not express on cell membrane.
Synonyms: hENT2; DER12; ENT2; HNP36
Tractability: Small molecule: it belongs to a druggable protein family. Antibody: UniProt places it where antibodies can reach, with high confidence; its Gene Ontology location is reachable by antibodies, with high confidence; UniProt predicts a signal peptide or a membrane-spanning region. PROTAC: ubiquitination databases record sites on it; its protein half-life has been measured; a small molecule that binds it is known.
Target class: Electrochemical transporter; SLC28 and SLC29 families of nucleoside transporters; SLC29 Facilitative nucleoside transporter family; Transporter; SLC superfamily of solute carriers
Gene: Protein-coding gene on chromosome 11 (66,362,520 to 66,372,476, reverse strand). Ensembl gene ENSG00000174669.
Subcellular location: Apical cell membrane; Basolateral cell membrane; Cell membrane
Pathways (Reactome):
Drug ADME: Azathioprine ADME
Transport of small molecules: Transport of nucleosides and free purine and pyrimidine bases across the plasma membrane
Gene Ontology:
Molecular function: adenine transmembrane transporter activity; cytidine transmembrane transporter activity; guanine transmembrane transporter activity; neurotransmitter transmembrane transporter activity; nucleobase transmembrane transporter activity; nucleoside transmembrane transporter activity; purine nucleoside transmembrane transporter activity; uracil transmembrane transporter activity; uridine transmembrane transporter activity
Biological process: adenine transport; adenosine transport; cytidine transport; guanine transmembrane transport; hypoxanthine transport; inosine transport; neurotransmitter transport; nucleobase transport; nucleoside transmembrane transport; nucleoside transport; purine nucleobase transmembrane transport; purine nucleoside transmembrane transport; pyrimidine-containing compound transmembrane transport; thymine transport; uracil transmembrane transport; urate transport; uridine transmembrane transport; guanine transport; neurotransmitter uptake; transport across blood-brain barrier; xenobiotic transmembrane transport
Cellular component: apical plasma membrane; basolateral plasma membrane; plasma membrane; nucleolus; membrane
Genetic constraint (gnomAD): Loss-of-function variants: 37 observed, 47.96 expected, observed/expected ratio (o/e) 0.77, 90% interval 0.59 to 1.01. The upper end of that interval is the gene's LOEUF score, 1.01, which puts it in group 4 of 6, group 1 being the genes least tolerant of losing a copy. Missense variants: 533 observed, 585.94 expected, observed/expected ratio (o/e) 0.91, 90% interval 0.85 to 0.98. Synonymous variants: 233 observed, 262.85 expected, observed/expected ratio (o/e) 0.89, 90% interval 0.8 to 0.99.
Homologues: Orthologues: chimpanzee SLC29A2 (99% identical), macaque SLC29A2 (97% identical), guinea pig SLC29A2 (92% identical), dog SLC29A2 (91% identical), pig SLC29A2 (91% identical), mouse Slc29a2 (89% identical), rat Slc29a2 (88% identical), rabbit SLC29A2 (72% identical), tropical clawed frog slc29a2 (60% identical), zebrafish slc29a2 (50% identical), Drosophila melanogaster Ent1 (33% identical). Paralogues in human: SLC29A1 (48% identical), SLC29A3 (31% identical), SLC29A4 (25% identical).
Diseases named in the same sentence as SLC29A2 in open-access papers:
SLC29A2 is named in the same sentence as 35 diseases in open-access papers, as found by Europe PMC text mining. Sharing a sentence is not in itself a finding about the gene and the disease. The quoted sentences say what the papers report.
hepatocellular carcinoma (5 papers, 2015 to 2023). A malignant tumor that arises from hepatocytes. "Similarly, SLC29A2 (rank 4) has been implicated in the carcinogenesis of hepatocellular carcinoma." (PMID 25569148, 2015). "SLC29A2, solute carrier family 29 member 2, is aberrantly upregulated and is a survival predictor in both hepatocellular carcinoma and mantle cell lymphoma." (PMID 35186733, 2022).
diabetes (3 papers, 2017 to 2025). "The SLC29A2 gene which encodes the protein ENT2 (Equilibrative Nucleoside Transporter 2) has been proved sensitive to dysregulation in diabetes and acts as a target of insulin signaling." (PMID 34021221, 2021).
leukemia (3 papers, 2016 to 2023). A malignant (clonal) hematologic disorder, involving hematopoietic stem cells and characterized by the presence of primitive or atypical myeloid or lymphoid cells in the bone marrow and the blood. "This was supported by increased AZA sensitivity of canine kidney and leukemia cell lines transfected with SLC28A1 compared to cells lines transfected with SLC29A1, SLC29A2, and SLC28A2." (PMID 36834962, 2023). "The mRNA amounts of the main nucleoside transporters (NT) and intracellular metabolizing enzymes (ME), hENT1, hENT2 (SLC29A2), hCNT1 (SLC28A1), hCNT2 (SLC28A2), hCNT3 (SLC28A3), DCK and cN-II (NT5C2), were measured in 50 pediatric leukemia cases by RQ-PCR." (PMID 27391351, 2016).
depression (2 papers, 2019 to 2023). "Gene SLC29A2 (MCMCglmm: pair-living, post mean = −1.65, pMCMC = 0.02; longevity, post mean = 2.30 ± 0.05, pMCMC = 0.04 ± 3.18 × 10−3) is linked to the development of depression." (PMID 36720880, 2023). "Other top associated probes were located in gene bodies of MAD1L1 (p-value = 5.16 × 10−6), SLC29A2 (p-value = 6.15 × 10−6) and AKT1 (p-value = 4.47 × 10−6), all genes associated before with development of depression." (PMID 31477683, 2019). "In conclusion, we have performed EWAS of depression symptomatology score in a unique cohort of elderly monozygotic twins and identified blood methylation levels at KLK8, DAZAP2, MAD1L1, SLC29A2, AKT1, and other genes, as well as several DMRs across the genome to be associated with this trait." (PMID 31477683, 2019).
colon cancer (1 paper, 2025). "It was stated that SLC29A2 was expressed at lower levels in colon cancer cell lines originating from metastatic sites than from primary sites." (PMID 41465541, 2025).
lung adenocarcinoma (1 paper, 2024). A carcinoma that arises from the lung and is characterized by the presence of malignant glandular epithelial cells. "In line with this, both SLC29A1 and SLC29A2 are more highly expressed in human lung adenocarcinoma relative to adjacent lungs, suggesting a role in human lung cancer." (PMID 38876105, 2024).
cancer (14 papers, 2013 to 2025). A tumor composed of atypical neoplastic, often pleomorphic cells that invade other tissues. "We found that the expression level of SLC29A1 (encoding hENT1) and SLC29A2 (encoding hENT2) in human fibroblasts was significantly lower than that in human cancer cell lines." (PMID 27137226, 2016). "related to proliferation and apoptosis of cancer cells and detected the changes of downstream target expression in CCA cells after further knockdown of AGAP2-AS1,including CDKN1A,ADNP2,SLC29A2 by qRT-PCR." (PMID 33522895, 2021). "Finally, coherent and high gene expression of SLC29A2, TK1 and HPRT1 was observed in the three cell lines considered, according to CCLE (Cancer Cell Line Encyclopedia), which enable alternative salvage pathways for purine and pyrimidine synthesis through thymidine and hypoxanthine, respectively." (PMID 35286311, 2022).
adenocarcinoma (1 paper, 2025). A common cancer characterized by the presence of malignant glandular cells. "Regarding AKRB7A2, SLC5A6, and SLC29A2, for the first time, a significant role in CRC adenocarcinoma development as well as in a healthy colon is presented." (PMID 41465541, 2025).
SLC29A2 also shares sentences with these, for which no sentence is quoted: tumor (11 papers); lymphoma (4); mantle cell lymphoma (4); colorectal cancer (3); infection (3); colitis (2); gastric cancer (2); neurodegenerative disease (2); Alzheimer disease (1); brain tumors (1); chronic lymphocytic leukemia (1); chronic myeloid leukemia (1); COVID-19 (1); glioblastoma (1); Huntington disease (1); injury (1); insomnia (1); lung carcinoma (1); lupus (1); oedema (1); ovarian carcinoma (1); pancreatic tumours (1); prostate carcinoma (1); renal carcinoma (1); schizophrenia (1); stomach cancer (1); systemic candidiasis (1).